GAS5 (growth arrest specific 5)
Diseases named in the same sentence as GAS5 in open-access papers (continued):
Sharing a sentence is not in itself a finding about the gene and the disease.
Sepsis (continued). "Specifically, upon GAS5 knockdown, TLR4 overexpression mitigates the reduction in inflammatory cytokines and subsequent cell death, an indication that GAS5 enhances sepsis-related inflammatory responses through altering the miR-23a-3p/TLR4 axis." (PMID 39941145, 2025). "That study reveals that GAS5 acts as a sponge for miR-23a-3p, increasing the expression of TLR4 and thereby promoting inflammation and apoptosis in sepsis." (PMID 39941145, 2025). "The lncRNA, growth arrest-specific 5 (GAS5), has increasingly been recognized as a key modulator in sepsis-induced organ injury." (PMID 37509452, 2023). "Therefore, GAS5 and miR-146a may interact with each other to participate in sepsis." (PMID 35112981, 2022). "Therefore, GAS5 and miR-146a may participate in sepsis and sepsis-ALI." (PMID 35112981, 2022). "The results showed that GAS5 and miR-146a were significantly downregulated in sepsis-ALI in comparison to that in the sepsis and control groups (p < 0.05)." (PMID 35112981, 2022). "This protective mechanism involved the GAS5-mediated sponging of miR-23a-3p, which stabilized and enhanced MITF activity and Nrf2 to preserve mitochondrial integrity and reduce lung injury in instances of sepsis." (PMID 39941145, 2025). "The high expression of MITF or GAS5 correlated with relatively lower autophagy intensity, attributable to the antioxidant effect of MITF-transcribed Nrf2, which in turn contributes to the maintenance of autophagic flux during sepsis." (PMID 37509452, 2023). "Lnc‐GAS5 did not relate to Th1 cells (p = 0.059) or IFN‐γ (p = 0.192); while negatively linked with Th17 cells (p = 0.002) and IL‐17A (p = 0.019) in sepsis patients." (PMID 35325494, 2022). "Correlation analysis showed that GAS5 and miR-146a were positively and significantly correlated across sepsis-ALI samples, but not sepsis samples and the control samples." (PMID 35112981, 2022). "Furthermore, lnc‐GAS5 was negatively related to CRP (p = 0.002) and APACHE II score (p = 0.004) in sepsis patients." (PMID 35325494, 2022). "In this study, the expression of GAS5 and miR-146a in patients with sepsis-induced acute lung injury (sepsis-ALI), sepsis patients without obvious complications (sepsis) and healthy controls were studied by RT-qPCR." (PMID 35112981, 2022). "Importantly, we found high expression of GAS5 in mice following sepsis, and its down-regulation led to alleviated myocardial depression and injury, with all the CLP-induced changes were reversed following GAS5 silencing." (PMID 33645622, 2021). "Here, our study explored the potential ceRNA network in septic mouse models and identified that lncRNA GAS5 could interact with miR-449b and HMGB1, and further promote the sepsis-induced myocardial depression with the activation of the NF-κB signaling pathway." (PMID 33645622, 2021). "LncRNA GAS5 might through HMGB1 and subsequent NF-κB promote sepsis-induced myocardial inhibition." (PMID 35720285, 2022). "Secondly, a detailed mechanism of lnc‐GAS5 in sepsis was not investigated." (PMID 35325494, 2022). "Interestingly, we showed that GAS5 and miR-146a were downregulated in both sepsis patients without obvious complications and sepsis-ALK patients." (PMID 35112981, 2022).
Cirrhosis (10 papers, 2018 to 2025). A chronic disorder of the liver in which liver tissue becomes scarred and is partially replaced by regenerative nodules and fibrotic tissue resulting in loss of liver function. "Patients with cirrhosis have reduced levels of GAS5, a long non-coding RNA (lncRNA) associated with the inhibition of hepatic fibrogenesis." (PMID 40868128, 2025). "Future studies will be addressed to verify whether GAS5 and miR-126-3p may be potential early/predictive circulating biomarkers in at high-risk patients (i.e. patients with cirrhosis and/or HBV, HCV chronic hepatitis)." (PMID 31235746, 2019). "The three disease phases with the highest levels of lncRNA GAS5 were cirrhosis, NASH, and simple steatosis." (PMID 40868128, 2025). "Regarding the different stages of the disease, the highest level of lncRNA GAS5 was observed in cirrhosis, followed by NASH, and then simple steatosis." (PMID 40868128, 2025). "Regarding the different stages of the disease, the highest level of lncRNA GAS5 was observed in cirrhosis (5.13 ± 0.17), NASH (4.1 ± 0.1), and simple steatosis (3.18 ± 0.62) (p < 0.001)." (PMID 40868128, 2025). "This is the first study that demonstrated that GAS5 levels are altered during fibrosis progression and cirrhosis development." (PMID 34769333, 2021). "This was the first study to reveal that levels of GAS5 differ during the progression of fibrosis and development of cirrhosis." (PMID 32413995, 2020). "Prior to the development of cirrhosis, GAS5 tissue expression positively correlated with fibrosis stage (r = 0.20, P = 0.20)." (PMID 32413995, 2020). "To evaluate the relationship between GAS5 and fibrosis stage, we analyzed its expression during each stage of fibrosis, with the exception of cirrhosis." (PMID 32413995, 2020). "Regarding different stages of the disease, the highest level of lncRNA GAS5 was in cirrhosis." (PMID 40868128, 2025). "As fibrosis progressed towards cirrhosis, however, plasma GAS5 was downregulated." (PMID 36979495, 2023). "Plasma GAS5 expression increased with fibrosis progression but decreased in the case of cirrhosis." (PMID 36979495, 2023). "Plasma levels of GAS5 were lower in patients with cirrhosis than in those with advanced fibrosis." (PMID 32413995, 2020). "However, patients with cirrhosis were an exception with plasma Gas5 lower in patients with cirrhosis than in patients with advanced fibrosis, which could be the consequence of functional decompensation at the cirrhosis stage." (PMID 39872125, 2024). "However, significant differences in tissue levels of lncRNA GAS5 were not shown in patients with advanced fibrosis and cirrhosis, a phenomenon that emphasizes the accuracy of the association between plasma levels and fibrosis stage." (PMID 34899344, 2021). "In cirrhosis (such as PBC), the gene GAS5 was screened out, which was preliminarily confirmed to be a biological marker of primary biliary cirrhosis and has a broad clinical application prospect." (PMID 34633988, 2021). "However, GAS5 was upregulated in F3 versus F < 2, and its expression was downregulated in NAFLD patients with cirrhosis (F4) versus patients with advanced fibrosis (F3)." (PMID 34769333, 2021). "Interestingly, we also observed elevated GAS5 expression in fibrosis rather than non-fibrosis, whereas GAS5 expression decreased in cirrhosis, as established in The Cancer Genome Atlas (TCGA) public database analysis." (PMID 32413995, 2020). "One study found higher GAS5 plasma expression in patients with NAFLD and advanced fibrosis but not cirrhosis." (PMID 40489530, 2025).
depression (9 papers, 2021 to 2025). "One core example is the targeting of lncRNA GAS5, which has been linked to cellular responses to stress and glucocorticoid regulation, with potential implications in depressive disorders." (PMID 40038891, 2025). "In mice models, GAS5 was studied for depression-like behaviors, and its downregulation was found to alleviate hippocampal neuronal damage." (PMID 39457495, 2024). "In mice with depression-like behaviors, GAS5 binds specifically to miR26-a to keep EGR1 active, consequently, EGR1 deactivates the PI3K/AKT pathway, subsequently, infectious factors are released and apoptosis of hippocampal cells occurs." (PMID 37620425, 2023). "In the present study, we confirmed that the inhibition of GAS5 alleviated microglial activation and mitochondrial dysfunction, thereby ameliorating depression-like behaviours in the depression model." (PMID 35230663, 2022). "Rg1 consistently increased the expression of SOCS3 and NRF2 in the depression model, whereas the GAS5 overexpression compromised this effect, as indicated by a notable decrease in the expression of SOCS3 and NRF2." (PMID 35230663, 2022). "A functional study revealed that GAS5 exhibits a protective effect in the depression model by downregulating GAS5 expression." (PMID 35230663, 2022). "Rg1 attenuated microglial activation and improved mitochondrial dysfunction in depression by downregulating GAS5 expression." (PMID 35230663, 2022). "In the present study, we revealed the expression of two downstream genes, NRF2 and SOCS3, was inhibited by the GAS5/EZH2 axis in the depression model." (PMID 35230663, 2022). "Rg1 treatment attenuated microglial activation and improved mitochondrial dysfunction, thereby alleviating depression-like behaviours by downregulating lncRNA GAS5." (PMID 35230663, 2022). "However, the overexpression of GAS5 partly compromised the protective effect of Rg1 on depression-like behaviours." (PMID 35230663, 2022). "The protective role of GAS5 inhibition was also proven in the depression model." (PMID 35230663, 2022). "Overall, our results indicated that GAS5 mediated the protective effect of Rg1 in depression." (PMID 35230663, 2022). "To investigate whether GAS5 mediated the protective effect of Rg1 in depression, we injected lentivirus-packaged GAS5 overexpressing plasmid (Lenti-GAS5) into the rat brain before Rg1 treatment and modeling." (PMID 35230663, 2022). "We conducted a secondary analysis of the psychological symptom burden in the LIMBIC CENC cohort to evaluate whether the levels of the four serum lncRNAs (VLDLR-AS1, MALAT1, NEAT1, GAS5) correlate to symptom burden (such as cognition, memory, depression or PTSD) after rmTBI." (PMID 38338752, 2024). "Therefore, we speculated that Rg1/GAS5 regulates mitochondrial dysfunction in depression by regulating the expression of NRF2." (PMID 35230663, 2022). "Moreover, the present study revealed the detailed mechanism of GAS5 in depression." (PMID 35230663, 2022). "Ginsenoside Rg1 not only down-regulates GAS5 expression through GAS5/EZH2/SOCS3/NRF2, reduces microglial activation, and improves mitochondrial dysfunction in depression but also alleviates acute ulcerative colitis by regulating the intestinal flora and microbial tryptophan metabolism." (PMID 39997718, 2025). "Finally, the levels of lncRNAs VLDLR-AS1, NEAT1, GAS5 and MALAT1 were analyzed for correlation with depression symptoms, measured using the Patient Health Questionnaire-9 (PHQ-9)." (PMID 38338752, 2024). "However, we failed to validate how Rg1 regulated GAS5 and whether Rg1 could regulate other lncRNA involved in the pathology of depression." (PMID 35230663, 2022).
diabetic cardiomyopathy (9 papers, 2022 to 2025). Diabetic cardiomyopathy is a disorder of the heart muscle in people with diabetes. "A recent study also found that GAS5 is involved in regulating the pathophysiological process of diabetic cardiomyopathy caused by NLRP3 inflammasome activation." (PMID 38561456, 2024). "LncRNA GAS5 regulates pyroptosis in the diabetic heart, possibly by targeting GAS5/miR-34b-3p/AHR to inhibit NLRP3 inflammatory vesicle activation in diabetic cardiomyopathy achieve." (PMID 37396588, 2023). "LncRNA GAS5 is down-regulated in cardiomyocytes with diabetic cardiomyopathy (DCM), and its overexpression suppresses the expression of NLRP3 and its downstream genes and caspase-1 activity, thus improving DCM." (PMID 37498354, 2023). "GAS5 expression was significantly down-regulated in the heart tissue of diabetic cardiomyopathy mice." (PMID 35619068, 2022). "However, LncRNA GAS5 inhibits NLRP3 (inflammasome) activation-mediated pyroptosis in diabetic cardiomyopathy by targeting miR-34b-3p/AHR." (PMID 36061542, 2022). "In addition, the findings suggest that the lncRNA GAS5/miR-21-5p axis may serve as a candidate therapeutic target for diabetic cardiomyopathy, while another study found that inhibition of ADAM17 may provide a promising approach." (PMID 37821982, 2023). "Overexpression of GAS5 can inhibit NLRP3 inflammasome activation-mediated pyroptosis, improve cardiac function and myocardial hypertrophy in diabetic cardiomyopathy mice." (PMID 35619068, 2022). "GAS5 acts as a competing endogenous RNA to enhance AHR expression by sponging miR-34b-3p and repressing NLRP3 (inflammasome) activation-mediated pyroptosis to improve diabetic cardiomyopathy." (PMID 36061542, 2022).
esophageal cancer (9 papers, 2018 to 2025). A primary or metastatic malignant neoplasm involving the esophagus. "The study found that GAS5 expression was down-regulated in esophageal cancer cell lines, while miR-196a was up-regulated, and GAS5 and miR-196a were negatively correlated in esophageal cancer cells." (PMID 30606744, 2019). "Although the effect of GAS5 is completely different in the two papers, the important role of GAS5 in esophageal cancer is undeniable." (PMID 30606744, 2019). "Taken together, these results indicated that IFN responses are positively regulated by GAS5 in esophageal cancer." (PMID 29745062, 2018). "To further analyze the effects of GAS5 on ESCC cell viability and mobility, we over‐expressed GAS5 in 2 esophageal cancer cell lines, KYSE30 and KYSE180." (PMID 29745062, 2018). "These genes were downregulated by GAS5 knockdown and upregulated by over‐expression of GAS5 in 2 esophageal cancer cell lines." (PMID 29745062, 2018). "The results of these two studies on GAS5 in esophageal cancer are contradictory." (PMID 30606744, 2019). "However, the role of GAS5 in esophageal cancer has two completely different views." (PMID 30606744, 2019). "And GAS5 expression in stage III and IV esophageal cancer tissue was significantly lower than that of stage I and II esophageal cancer tissue." (PMID 30606744, 2019). "To further confirm that IFN induces the lncRNA GAS5 via the JAK‐STAT signaling pathway, we simultaneously treated esophageal cancer cells with IFN‐β and the JAK inhibitor ruxolitinib." (PMID 29745062, 2018).
fibrosis (9 papers, 2020 to 2025). the formation of excess fibrous connective tissue in an organ or tissue in a reparative or reactive process. "Notably, urinary GAS5 maintained high diagnostic efficacy across fibrosis subgroups, achieving the highest AUC in the severe fibrosis group (n = 16), despite its limited sample size, further supporting its diagnostic capability for renal fibrosis." (PMID 40685500, 2025). "Quantitative analysis revealed markedly decreased GAS5 expression levels in the renal fibrosis group compared with both healthy controls (p < 0.001) and non-fibrosis pathological counterparts (p < 0.001)." (PMID 40685500, 2025). "Studies have found that GAS5 can attenuate cardiac fibrosis by regulating PTEN/MMP-2 signaling pathway and improve cardiac function by inhibiting Wnt/β-catenin signaling pathway." (PMID 35619068, 2022). "The mild fibrosis subgroup exhibited markedly elevated GAS5 expression compared to non-fibrotic controls (p = 0.014), with subsequent significant increments observed in moderate (vs. mild, p < 0.001)." (PMID 40685500, 2025). "The expression of Gas5 was significantly higher in the tissues and plasmas of patients with advanced fibrosis than in those without fibrosis." (PMID 39872125, 2024).
Insulin resistance (9 papers, 2020 to 2025). Increased resistance towards insulin, that is, diminished effectiveness of insulin in reducing blood glucose levels. "Given that mitochondrial dysfunction is a hallmark of insulin resistance, these findings support the role of gas5 in mitochondrial regulation, in concurrence with a study demonstrating its mitochondrial localization and role in mitochondrial metabolic regulation." (PMID 40332318, 2025). "Our data in DIO mice which present with insulin resistance showed that GAS5 levels were reduced in the hippocampus." (PMID 36609440, 2023). "The lncRNA Gas5 with functional annotation, which was reported to play an important role in pancreatic β-cell function and peripheral insulin resistance, was identified in the microarray." (PMID 35464075, 2022). "The serum level of another lncRNA, growth arrest-specific transcript 5 (GAS5), has been correlated with T2DM prevalence and its downregulation has been associated with insulin resistance." (PMID 31999937, 2020). "OIP5-AS1 has little or non-studies in obesity, whereas GAS5 has been implicated in obesity and insulin resistance by targeting some miRNAs, such as miR-21, that have been implicated in obesity, as well as in lung diseases." (PMID 37047453, 2023). "Therefore, our future studies may focus on the involvement of GAS5 in the regulation of insulin-resistance in PCOS." (PMID 33308258, 2020).
mesothelioma (8 papers, 2014 to 2024). A usually malignant and aggressive neoplasm of the mesothelium which is often associated with exposure to asbestos. "In this study, only GAS5 was reliably proven as a marker for the detection of mesothelioma using liquid biopsies." (PMID 32435497, 2020). "The median plasma level of normalized GAS5 was 4.05 (IQR 2.94–8.38) in mesothelioma patients and 0.62 (IQR 0.28–0.96) in asbestos-exposed controls." (PMID 32435497, 2020). "Another lncRNA involved in mesothelioma is GAS5, with a reported low expression in mesothelioma cells." (PMID 32723695, 2020). "We found a significant up-regulation of GAS5 in plasma of mesothelioma patients and mesothelioma cell lines, confirming our initial in silico analysis of published expression data based on tissue samples of pleural mesothelioma." (PMID 32435497, 2020). "The difference of circulating GAS5 in plasma between mesothelioma patients and asbestos-exposed controls was statistically significant (p < 0.0001)." (PMID 32435497, 2020). "The benefit of GAS5 for the detection of mesothelioma at early stages using plasma samples taken before clinical diagnosis still needs to be validated in a prospective study." (PMID 32435497, 2020). "Earlier experimental studies in mice showed GAS5 (growth arrest specific transcript 5) gene deletion in asbestos driven mesothelioma." (PMID 24885398, 2014). "In order to find an explanation why GAS5 expression should be high in tumor cells, we compared GAS5 expression to known mesothelioma markers and found that GAS5 expression was positively correlated to podoplanin expression." (PMID 24885398, 2014). "Another study supported our findings, suggesting that circulating GAS5 could be a prognostic marker before and after chemotherapy in mesothelioma patients." (PMID 38413635, 2024). "Thus, for early diagnosis it will also be necessary to validate GAS5 as well as the previously identified RP1-86D1.3 in a prospective study regarding their potential to detect mesothelioma in prediagnostic plasma samples and to complement calretinin and mesothelin." (PMID 32435497, 2020). "To date, GAS5 overexpression in tumor has been reported only in mesothelioma, where the Authors hypothesized, as a possible explanation of the discrepancy, that high GAS5 expression in that cellular milieu does not only control cell cycle but also act as a natural sponge for miRNAs." (PMID 26895470, 2016). "Additionally, the observed up-regulation of GAS5 in mesothelioma tissues as well as in plasma of mesothelioma patients suggested that the presence of circulating GAS5 in plasma might be a direct effect of the tumor, e.g., via the secretion of lncRNA containing extracellular vesicles." (PMID 32435497, 2020). "Using the 2-ΔΔCt method to assess different expressions between mesothelioma cell lines and MeT-5A as control revealed an up-regulation of AFAP1-AS1, GAS5, and LOC84856 in at least three of the mesothelioma cell lines." (PMID 32435497, 2020). "Eleven asbestos-exposed controls were excluded from analyses because raw Ct values of GAS5 or RPLP0 in plasma were ≥ 35, resulted in 22 mesothelioma patients and 31 asbestos-exposed controls appropriate for analysis." (PMID 32435497, 2020).